TSPAN7 (tetraspanin 7)
Diseases named in the same sentence as TSPAN7 in open-access papers (continued):
Sharing a sentence is not in itself a finding about the gene and the disease.
glioma (2 papers, 2023 to 2024). A benign or malignant brain and spinal cord tumor that arises from glial cells (astrocytes, oligodendrocytes, ependymal cells). "In this study, through analyzing a large number of glioma cohorts, we reported that TSPAN7, a member of the tetraspanin family, decreased in high-grade gliomas and low expression was associated with poor prognosis in glioma patients." (PMID 36845098, 2023). "Meanwhile, the expression pattern of TSPAN7 was verified in glioma clinical samples and glioma cell lines by qPCR, Western Blotting and immunofluorescence." (PMID 36845098, 2023). "In summary, our findings initially illustrate that TSPAN7 can be a novel effective indicator for predicting the clinical stage, and has multifaceted prognostic value in glioma." (PMID 36845098, 2023). "To further confirm its reliability, we explored the relationship between TSPAN7 expression and the prognosis of glioma patients in various public datasets." (PMID 36845098, 2023). "To explore the expression pattern of TSPAN7 in glioma, first we analyzed the expression of TSPAN7 in pan-cancer." (PMID 36845098, 2023). "All these results indicated that TSPAN7 expression was closely related to the malignancy and prognosis of glioma." (PMID 36845098, 2023). "Both survival analysis and multivariate Cox regression analysis in multiple datasets revealed that low TSPAN7 was an independent predictor of prognosis in glioma patients." (PMID 36845098, 2023). "As IDH mutation and 1p/19q deletion status are the dominant molecular marker for glioma patients, we investigate the relationship between them and TSPAN7 expression in TCGA and CGGA." (PMID 36845098, 2023). "We utilized multiple public databases to analyze the function of TSPAN7 in glioma and found that TSPAN7 was significantly decreased in GBM compared with LGG." (PMID 36845098, 2023). "Based on these results, we speculate that TSPAN7 is a potential prognostic biomarker and may be developed as a clinical therapeutic target for glioma." (PMID 36845098, 2023). "To further clarify the biological functions that TSPAN7 may be involved during glioma progression, we divided the patients into two groups according to the median expression of TSPAN7 in TCGA glioma cohorts and GO enrichment analysis were performed." (PMID 36845098, 2023). "Here, we used several public online databases, including The Cancer Genome Atlas (TCGA), Chinese Glioma Genome Atlas (CGGA) and Gene Expression Omnibus (GEO), to analyze the relationship among the expression of TSPAN7, clinicopathological features, prognosis and immune microenvironment in glioma." (PMID 36845098, 2023). "Overall, these findings support the speculation that TSPAN7 might be involved in the regulation of tumor progression of gliomas." (PMID 36845098, 2023). "Wound-healing assays also demonstrated that over-expression TSPAN7 could inhibited U87 glioma cell migration." (PMID 36845098, 2023). "On the basis of these results above, we could infer that high expression of TSPAN7 could inhibit glioma progression." (PMID 36845098, 2023). "Combined with the findings of this study, we speculate that, during the malignant progression of glioma, with the gradual decrease of TSPAN7, Ca2+ influx increased, and the biological behavior such as oxidative stress, cell proliferation, and migration of tumor cells gradually increase." (PMID 36845098, 2023). "Therefore, we speculate that TSPAN7 is of great significance for predicting the prognosis of glioma patients." (PMID 36845098, 2023). "Therefore, we further evaluated whether changes in TSPAN7 expression have an influence on the malignant biological behavior of glioma cells." (PMID 36845098, 2023). "In the present study, our results indicated that TSPAN7 may have an anti-tumor effect on glioma." (PMID 36845098, 2023). "Lentiviral plasmids were used to overexpress TSPAN7 in U87 and LN229 glioma cell lines to explore the anti-tumor role of TSPAN7 in glioma." (PMID 36845098, 2023).
glioma (continued). "First, we analyzed TSPAN7 expression in normal glial cell line and glioma cell lines by Western Blotting and found that it was expressed at higher levels in HA1800 than in glioma cell lines." (PMID 36845098, 2023). "However, the function and expression characteristics of TSPAN7 have never been reported in glioma." (PMID 36845098, 2023).
hepatocellular carcinoma (2 papers, 2020 to 2023). A malignant tumor that arises from hepatocytes. "According to a study on the expression of TSPANs in the Oncomine database about hepatocellular carcinoma, the expression of TSPAN7, TSPAN12 and TSPAN28 (CD81) proteins were lower in hepatocellular carcinoma cells than in normal liver tissue." (PMID 37752917, 2023). "Our study evaluated the expression and function of the TSPANs family in digestive cancers and explored TSPAN7 in hepatoma cells in detail." (PMID 32694936, 2020). "Therefore, TSPAN7 may be a new potential biomarker that can provide a new therapeutic strategy for hepatocellular carcinoma." (PMID 32694936, 2020). "According to Wurmbach’s study, we learned that TSPAN7 and TSPAN12 are reduced in hepatocellular carcinoma." (PMID 32694936, 2020). "Among four data sets, it was found that the expression of TSPAN7, TSPAN12, and TSPAN28 was lower in hepatocellular carcinoma patients than it was in the normal population." (PMID 32694936, 2020).
Obesity (2 papers, 2024 to 2025). Accumulation of substantial excess body fat. "In a previous study, we identified Tspan7 as a candidate gene in subcutaneous adipose tissue through obesity-related gene screening." (PMID 40368161, 2025). "We previously identified tetraspanin 7 (Tspan7) as a candidate gene influencing body weight in an obesity-related gene screening study." (PMID 40368161, 2025). "Tspan7 expression in the iWAT and eWAT of 38-week-old ND-fed obesity-prone male 6N mice was significantly lower (p = 0.06 and p < 0.01, respectively) than that in the obesity-resistant male 6J mice of the same age." (PMID 40368161, 2025). "In our previous study on obesity using Tspan7 transgenic mice, dilated kidneys were frequently observed in the mice." (PMID 39000307, 2024). "•TSPAN7 modulation offers potential for obesity and metabolic disease therapies." (PMID 40368161, 2025). "Given that the tetraspanin family plays essential roles in cellular organization and signaling, we hypothesized that TSPAN7 might regulate adipocyte function, lipid storage, and fat distribution, thereby influencing metabolic homeostasis and obesity." (PMID 40368161, 2025). "This suggests that targeting TSPAN7 in adipose tissue may offer therapeutic benefits for metabolic disorders such as obesity and type 2 diabetes." (PMID 40368161, 2025). "An understanding of the role of TSPAN7 in fat distribution could provide crucial insights into obesity pathogenesis and metabolic health, potentially leading to novel therapeutic strategies for obesity and related metabolic diseases." (PMID 40368161, 2025). "Recently, while conducting a study on obesity, we encountered a hydronephrosis-like phenomenon in genetically engineered mice expressing Cre recombinase under the adiponectin (Adipoq) promoter, targeting tetraspanin 7 (Tspan7) in an adipose-tissue-specific manner on a C57BL/6 background." (PMID 39000307, 2024).
soft tissue sarcoma (2 papers, 2020 to 2023). A malignant neoplasm arising from muscle tissue, adipose tissue, blood vessels, fibrous tissue, or other supportive tissues excluding the bones. "TSPAN7 is also downregulated in soft tissue sarcoma and is associated with better survival." (PMID 33033514, 2020).
viral infections (2 papers, 2021 to 2025). "Tspan7, a transmembrane glycoprotein functionally involved in many different viral infections was downregulated 10 fold, and neuron development genes Tenm3 and Dpysl3 were down 19.4 fold and 26.8 fold respectively in Prol/CJ− vs Prol/Nl cells." (PMID 40434970, 2025). "Among all the cell surface proteins, Cluster of Differentiation (CDs such as CD9, CD63, CD81, CD151, CD82) and Tetraspanin (Tspan) types that includes Tspan7 and Tspan9 have been reported to be involved in viral infections." (PMID 33968023, 2021).
astrocytoma (1 paper, 2023). "Similarly, according to the classification of different histological types, TSPAN7 showed the lowest expression in GBM, followed by astrocytoma." (PMID 36845098, 2023).
atherosclerosis (1 paper, 2025). A disease characterized by the build-up of fatty material and calcium deposition in the arterial wall resulting in partial or complete occlusion of the arterial lumen. "The results showed a significant upregulation of migrasome‐associated genes, including TSPAN4, TSPAN7, EOGT, and PIGK, in the model group, further supporting the high expression of migrasomes in atherosclerosis." (PMID 40548932, 2025).
autism spectrum disorder (1 paper, 2023). A spectrum of developmental disorders that includes autism, and Asperger syndrome. "TSPAN7 is related to various neurological disorders including autism spectrum disorder (ASD)." (PMID 36625203, 2023).
Autoimmunity (1 paper, 2020). The occurrence of an immune reaction against the organism's own cells or tissues. "Thus, Tspan7 autoimmunity can appear years before disease onset and may, therefore, be useful in disease prediction, but its value may be limited by the low proportion of patients positive for the antibodies." (PMID 32314012, 2020).
Batten disease (1 paper, 2025). "A recent paper exploring the proteomic changes in microglia with another LSD, Batten disease caused by loss of CLN3, identify similar changes to those seen here, including increased TTYH3, PTTG1IP, LAMTOR3, PSAP, STARD3NL, TSPAN7, TMEM192 and NPC1." (PMID 40608809, 2025).
gastric cancer (1 paper, 2020). A primary or metastatic malignant neoplasm involving the stomach. "The results of Chen’s research indicate that TSPAN7 is underexpressed in gastric cancer." (PMID 32694936, 2020).
hydronephrosis (1 paper, 2024). Collection of urine in the renal pelvis that results in dilatation of the renal pelvis and calyces. "We investigated the cause of hydronephrosis by analyzing tetraspanin 7 (Tspan7) gene-modified mice, which had shown a high incidence of hydronephrosis-like symptoms." (PMID 39000307, 2024). "Because the incidence of a hydronephrosis-like pathology in Tspan7 transgenic mice depended on the location of genomic mutations assumed to have occurred during the mouse generation process, gene expression analysis was also performed for each of these genomic mutations." (PMID 39000307, 2024). "We examined the incidence of hydronephrosis-like pathology in Adipoq-Cre mice used to generate Tspan7 transgenic mice." (PMID 39000307, 2024). "Our data showed that in Tspan7 transgenic mice exhibiting a hydronephrosis-like pathology, not only Otc, the gene most adjacent to Tspan7, but also other contiguous genes, Xk, Dynlt3, and Mid1ip1, were affected." (PMID 39000307, 2024). "The incidence of hydronephrosis-like pathology was higher in males than in females in both Tspan7 transgenic and Cre driver mice." (PMID 39000307, 2024). "We questioned how Cre-expression cassette integration would cause renal abnormalities and speculated that the X chromosome might be involved in hydronephrosis-like phenotypes based on our observations and the location of Tspan7 on the chromosome." (PMID 39000307, 2024). "In light of this, the hydronephrosis-like pathology we frequently observed in Tspan7 transgenic mice may be another example of a contiguous gene syndrome." (PMID 39000307, 2024). "We found that urea cycle gene Otc, which, like Tspan7, is located on the X chromosome, may be involved in the onset and progression of hydronephrosis through its effect on the kidneys via the disruption of the urea cycle in the liver and subsequent ammonia accumulation." (PMID 39000307, 2024). "However, mice with a liver-to-kidney weight ratio <3.08 and high blood ammonia levels were common among mice with hydronephrosis regardless of the genomic manipulations of the Tspan7 transgenic mice, suggesting that Otc may also be involved in hydronephrosis in wild-type and Cre driver mice." (PMID 39000307, 2024).
Hyperammonemia (1 paper, 2024). An increased concentration of ammonia in the blood. "We surmised that if manipulation of Tspan7 triggered X-linked contiguous gene syndromes and Tspan7 transgenic mice developed OTCD-like symptoms such as hyperammonemia, the expression levels of genes other than Otc may also be affected." (PMID 39000307, 2024).
Insulin resistance (1 paper, 2025). Increased resistance towards insulin, that is, diminished effectiveness of insulin in reducing blood glucose levels. "Mechanistically, TSPAN7 deficiency promoted subcutaneous fat expansion, alleviating metabolic stress on visceral fat, a major contributor to insulin resistance." (PMID 40368161, 2025).
intestinal cancer (1 paper, 2020). "In gastric and intestinal cancer cells, TSPAN7 expression was not significantly different from that of the normal cells." (PMID 32694936, 2020).
meningioma (1 paper, 2018). A generally slow growing tumor attached to the dura mater. "Similarly, TSPAN7 downregulation has been reported in more aggressive types of meningioma." (PMID 29662628, 2018). "RUNDC3B, SCG2, SLC1A3, EXT1 (as well as RHOBTB3, TSPAN7, CAV2, MLPH) were part of the NF2/SMARCB1 expression subclass of a recent study on genomic profiling of meningioma." (PMID 29662628, 2018).
non-small cell lung carcinoma (1 paper, 2024). A group of at least three distinct histological types of lung cancer, including non-small cell squamous cell carcinoma, adenocarcinoma, and large cell carcinoma. "However, overexpressed Tspan7 in non-small cell lung cancer (NSCLC) cells was shown to markedly increase tumor volume in vivo, and significantly promote the migration of NSCLC cells by facilitating the EMT process." (PMID 38389703, 2024).
pancreatic ductal adenocarcinoma (1 paper, 2025). An infiltrating adenocarcinoma that arises from the epithelial cells of the pancreas. "In pancreatic ductal adenocarcinoma, TSPAN7 inhibits RAD51AP1‐mediated DSB repair, activating cGAS‐STING signalling to increase CD8+ T‐cell infiltration and improve chemoimmunotherapy efficacy." (PMID 41350246, 2025).
sarcoma (1 paper, 2024). A usually aggressive malignant neoplasm of the soft tissue or bone. "In terms of gene signatures, an immune-related five-gene signature based on MYBL2, FBN2, TSPAN7, GCSH, and DDX39B is a prognostic biomarker for sarcoma patients." (PMID 38240704, 2024).
urothelial carcinoma (1 paper, 2023). A malignant neoplasm derived from the transitional epithelium of the urinary tract (urinary bladder, ureter, urethra, or renal pelvis). "TSPAN7 exerts an anti-tumor effect via the PTEN/PI3K/AKT pathway in urothelial carcinoma." (PMID 36512456, 2023).
tumor (22 papers, 2018 to 2025). "Due to the association between abnormal expression of TSPAN7 and some tumor progressed system, we selected some related hallmark gene sets from MSigDB and performed ssGSEA to calculate the activity of each pathway in TCGA cohorts." (PMID 36845098, 2023). "In the current study, we first identified that the expression of TSPAN7 was significantly associated with tumor stage and grade in human BCa, and that low TSPAN7 expression was an independent predictive factor of overall survival (OS)." (PMID 33489923, 2020). "Among these, RACGAP1, RARRES3, TPX2, MMP28, GPR87, and KIF14 were upregulated and positively associated with poor survival, whereas TSPAN7 was downregulated and identified as a tumor suppressor." (PMID 33033514, 2020). "First, via reverse transcription and quantitative real-time PCR (qRT-PCR), we observed downregulation of TSPAN7 in BCa tissues samples and cell lines and found that this downregulation was associated with a relatively high tumor stage and tumor grade." (PMID 33489923, 2020). "Meanwhile, a recent study indicated that high Tspan7 expression may be used to predict poor prognosis and high risk of metastasis in patients with pancreatic cancer, particularly those with Tumor-Node-Metastasis stages I and II." (PMID 38389703, 2024). "Subsequent studies found that Tspan7 was positively associated with disease-free survival and tumor-specific survival in ccRCC patients, and that the expression of Tspan7 protein in vessels may serve as a potential prognostic marker in ccRCC." (PMID 38389703, 2024). "Low expression of TSPAN7 were also associated with immune response which could influence the tumor-immune cell interaction." (PMID 36845098, 2023). "Notably, the protective effect of non-antigen-specific IgA disappeared in both RAG1-deficient and NSG mice and tumour-derived TSPAN7 and BDNF antibodies showed decreased anti-tumour effects, consistent with the capacity to transcytose through tumour cells." (PMID 33536615, 2021). "TSPAN7 expression was associated with tumor stage (p=0.01) and tumor grade (p=0.03) in BCa." (PMID 33489923, 2020). "The polymeric immunoglobulin receptor (pIgR) mediated IgA transcytosis also contributed to the tumor control, as pIgR knockout reduced BDNF and TSPAN7 IgA mediated tumor control." (PMID 40356924, 2025). "Firstly, the study provides strong in vitro evidence but lacks in vivo experiments using animal models, limiting the understanding of TSPAN7’s role in CRC within the tumor microenvironment." (PMID 41031049, 2025). "Functional studies confirmed that inhibition of tetraspanin 7 expression stopped tumor growth and the EMT process, whereas overexpression of tetraspanin 7 had the opposite effect." (PMID 39031113, 2024). "Accumulating evidence suggests that Tspan7 plays a dual role as a tumor suppressor or pro-oncogenic factor in different types of cancer." (PMID 38389703, 2024). "For instance, Tspan7 has been shown to exert antitumor effects on bladder cancer by inhibiting tumor growth via the PTEN/PI3K/Akt pathway." (PMID 38389703, 2024). "While CD4+ T cells primarily mediated anti-tumor immunity and Tregs primarily mediated pro-tumour immunity, these were consistent with our previous result that patients with high TSPAN7 expression had better prognosis." (PMID 36845098, 2023). "In past studies, multiple prognostic models have been constructed because of the differential expression of CD74 or TSPAN7 between tumor and normal tissues." (PMID 36911401, 2023). "Of note, TSPAN7 was mainly expressed in glial cells in which the expression in tumor cell was lower than normal cell such as OPC and astrocyte consistent with our previous findings." (PMID 36845098, 2023). "Results in TCGA dataset showed that tumor with low TSPAN7 expression had dominantly more M2 macrophages infiltrated compared to other immune cells." (PMID 36845098, 2023).